VDR (vitamin D receptor)
Diseases named in the same sentence as VDR in open-access papers (continued):
Sharing a sentence is not in itself a finding about the gene and the disease.
tuberculosis (continued). "We found that M. tuberculosis-stimulated macrophages from persons with previous extrapulmonary TB had higher expression of VDR compared to macrophages from persons with previous pulmonary TB, TB contacts with latent M. tuberculosis infection, and uninfected contacts." (PMID 31039752, 2019). "The aim of the present study was to look for associations between polymorphisms in VDR and NRAMP1 genes and susceptibility to infection and disease with Mycobacterium tuberculosis, as indicated by a positive TST, and the development of TB in the Venezuelan population." (PMID 26578819, 2015). "Moreover, the combination of VDR genotype and 25(OH)VD3 serum level seemed to affect clinical outcome in tuberculosis." (PMID 26894582, 2016). "First, HIV status might influence tuberculosis incidence; so, the stratification of HIV status would further reveal the relationship between VDR gene SNPs and tuberculosis." (PMID 24349552, 2013). "We evaluated macrophage expression of VDR, TLR2, cathelicidin, and TNF-α, and production of IL-1β in HIV-seronegative persons with previous EPTB, previous pulmonary TB, latent M. tuberculosis infection, and uninfected TB contacts." (PMID 31039752, 2019).
COVID-19 (64 papers, 2020 to 2025). A disease caused by infection with severe acute respiratory syndrome coronavirus 2. "A study comparing VDR polymorphisms between patients with severe and mild forms of COVID-19 showed that the TT genotype of the rs11568820 polymorphism appears to have a protective effect by reducing the risk of severe disease and hospitalization." (PMID 39781525, 2025). "In the context of COVID-19, a study conducted in Iran genotyped eight VDR polymorphisms (rs7975232, rs1544410, rs731236, rs2228570, rs757343, rs739837, and rs11568820) in 500 hospitalized patients using the PCR-RFLP method." (PMID 40278307, 2025). "This study aims to address these gaps by evaluating vitamin D levels and VDR polymorphisms and their association with clinical and biological outcomes in patients hospitalized with severe influenza and COVID-19 during the 2023–2024 winter season." (PMID 41301713, 2025). "A separate study in Turkey examined the relationship between VDR polymorphisms (rs2228570, rs7975232, rs731236, and rs1544410) and COVID-19 prognosis using genetic data from 297 COVID-19 patients in the Marmara University Medical Genetics Biobank." (PMID 40278307, 2025). "Elevated VDR expression in nasopharyngeal tissue correlated with lower COVID-19 risk (OR = 0.40, p = 0.05) and inversely with 25(OH)D levels (r = –0.61, p = 0.04)." (PMID 40904798, 2025). "In summary, our findings demonstrate that the protective effects of vitamin D in COVID-19 are more closely associated with local VDR expression and innate antimicrobial pathways, particularly DEFA1-3, than with systemic 25(OH)D concentrations alone." (PMID 40904798, 2025). "Existing studies on VDR polymorphisms and COVID-19 severity have yielded mixed results, a variability likely influenced by differences in study populations and by the viral variants circulating at the time of patient recruitment." (PMID 41301713, 2025). "This study aimed to investigate the role of vitamin D levels and vitamin D receptor polymorphisms in the clinical outcomes of patients hospitalized with COVID-19 or severe influenza during the 2023–2024 winter season." (PMID 41301713, 2025). "In a cross-sectional analysis among 500 COVID-19 patients with different severities, the associations of VDR-SNPs with the symptoms of COVID-19 varied between patients with different severities." (PMID 38702336, 2024). "To date, several studies have examined the association between VDR polymorphisms and COVID-19 severity or susceptibility." (PMID 38702336, 2024). "Recent studies suggest that vitamin D levels and genetic variations in the vitamin D receptor (VDR) gene significantly impact the severity and outcomes of COVID-19, especially in the infections caused by Delta and Omicron variants." (PMID 39406981, 2024). "Our study was a descriptive analysis and cannot reveal any causal relationship between VDR polymorphisms and COVID-19 severity." (PMID 38702336, 2024). "There are publications studying the potential impact of genetic variations in the VDR gene (including rs2228570) on COVID-19 susceptibility and severity, but their number is small and the results differ significantly." (PMID 37049620, 2023). "Namely, VDR gene polymorphism at rs1544410 (BsmI) site revealed that people with CC genotype have OR = 0.44 95% CI (0.21–0.91) asymptomatic COVID-19 than those with TT and TC genotypes under the recessive mode of inheritance." (PMID 36833234, 2023). "In total, 100 Jordanian patients with confirmed COVID-19 were genotyped for the VDR ApaI, FokI, and TaqI variants using the polymerase chain reaction-restriction fragment length polymorphism (PCR-RFLP) method." (PMID 38138892, 2023). "Four case-control studies from Italy, Iran, and Cyprus reported the association between VDR polymorphism and COVID-19 susceptibility, while one study from Iran reported the association between VDR polymorphism and COVID-19 mortality." (PMID 36830936, 2023).
COVID-19 (continued). "From haplotype analysis, the GGT haplotype of VDR (block 3) was found to be statistically significantly associated with asymptomatic COVID-19 susceptibility OR = 3.12 (1.07–9.10)." (PMID 36833234, 2023). "With regard to long-COVID-19 symptoms, the VDR heterozygous ApaI and wild-type TaqI genotypes were significantly associated with persistent fatigue and muscle pain after COVID-19 (p ˂ 0.05)." (PMID 38138892, 2023). "COVID-19 severity, the most commonly reported long-COVID-19 symptoms that lasted for >4 weeks from the onset of infection, and other variables were analyzed according to VDR genetic variants." (PMID 38138892, 2023). "Among patients with both mild/moderate and severe/critical COVID-19, VDR genetic variants exhibited substantial relationships with various clinical outcomes, including disease severity and shortness of breath." (PMID 38138892, 2023). "In particular, VDR and GC polymorphisms should be taken into account as potential effect modifiers in studies aiming to determine causality of vitamin D and COVID-19-related outcomes." (PMID 36830936, 2023). "The present study evaluated the associations of ApaI, FokI, and TaqI VDR variants with various COVID-19 symptoms lasting over 4 weeks." (PMID 38138892, 2023). "The associations between VDR TaqI polymorphisms and long-COVID-19 symptoms should be investigated in larger and more diverse ethnic populations." (PMID 38138892, 2023). "Recently published systematic review and meta-analysis on the relation between ACE1, ACE2, TMPRSS2, IFITM3, and VDR genes polymorphisms and COVID-19 outcomes has elucidated the potential involvement of these SNPs in COVID-19 outcomes." (PMID 36743382, 2023). "In our study, the VDR Fok I homozygous FF genotype and F allele were significantly more represented in COVID-19 patients as compared to the control group." (PMID 36085364, 2023). "Another important aspect of the vitamin D-COVID-19 theory is that common polymorphisms in the VDR and GC genes have been shown to influence the susceptibility and severity of COVID-19." (PMID 36830936, 2023). "Block 11 (G allele of rs731236 (TaqI) and T allele of rs1544410 (BsmI)) of VDR was found to be associated (p = 0.028) with increased odds of asymptomatic COVID-19 95% CI is between 1.1 and 4.61." (PMID 36833234, 2023). "This study investigated the associations of the major VDR genetic variants ApaI, FokI, and TaqI with the severity and long post-infection symptoms of COVID-19." (PMID 38138892, 2023). "It is also one of the few studies evaluating the association of single-nucleotide polymorphisms in the VDR gene, in particular rs2228570, with susceptibility to COVID-19." (PMID 37049620, 2023). "VDR TaqI is a possible genetic variant related to both COVID-19 severity and long-COVID-19 symptoms among Jordanian individuals." (PMID 38138892, 2023). "VDR activation can also inhibit S-phase kinase-associated protein 2 (Skp2), which plays a key role in the viral replication mechanism in COVID-19." (PMID 35807895, 2022). "Many studies have already assessed the relationship between polymorphisms of the VDR gene and susceptibility to COVID-19, and some are in progress." (PMID 36553614, 2022). "In the case of polymorphisms within VDR, the meta-analysis was possible for the association of rs2228570 and rs731236 with COVID-19 severity." (PMID 35949487, 2022). "The main objective of the present study is to elucidate effects of naturally occurring variants within ACE1, ACE2, TMPRSS2, IFITM3 and VDR genes on clinical severity of COVID-19 and/or the outcome of SARS-CoV-2 infection." (PMID 35949487, 2022). "Recently, VDR gene polymorphisms were described to be independently associated with COVID-19 severity and survival." (PMID 35757617, 2022).
COVID-19 (continued). "Another study showed that vitamin D receptor-deficient mice significantly reduced the expression of tight junction proteins specifically in the lungs compared to wild-type mice, making the role of vitamin D in reducing SARS−CoV−2 infection relevant since COVID-19 also affects the lungs." (PMID 35422757, 2022). "The purpose of this research was to determine the relationship between the genotypes of the TaqI polymorphism of VDR gene and the clinical forms of COVID-19 in Cuban patients." (PMID 38624931, 2021). "There are signs of association between the risk of developing COVID-19 and the genotypes of the TaqI polymorphism of the VDR gene in the studied Cuban patients." (PMID 38624931, 2021). "Specific SNPs located in the genes GC, DHCR7/NADSYN1, and VDR were associated with the critical COVID-19 condition among patients." (PMID 34835935, 2021). "Therefore, in the present study, we aimed to compare VDR polymorphisms in severe and mild COVID-19 patients." (PMID 38702336, 2024). "Therefore, in the present study, we aim to compare VDR polymorphisms in severe and mild COVID-19 patients." (PMID 38702336, 2024). "The associations of vitamin D receptor (VDR)- single nucleotide polymorphisms (SNPs) with the symptoms of COVID-19 may vary between patients with different severities of COVID-19." (PMID 38702336, 2024). "In one study, eight VDR polymorphisms were genotyped for 500 hospitalized patients with COVID-19 in Iran; six VDR polymorphisms displayed significant associations with disease severity and shortness of breath in both mild/moderate and severe/critical disease groups." (PMID 38138892, 2023). "The present study evaluated possible associations between VDR ApaI, FokI, and TaqI variants and COVID-19 severity based on the symptoms experienced during the period of infection, as well as long-COVID-19 symptoms lasting over 4 weeks from the onset of infection, among Jordanian patients." (PMID 38138892, 2023). "We also investigated whether vitamin D receptor (VDR) FokI polymorphism could be a genetic marker for COVID-19 susceptibility." (PMID 36085364, 2023). "VDR polymorphisms including FokI (rs2228570, exon 2, C > T), TaqI (rs731236, exon 9, A > G) and BsmI (rs1544410, intron 8, G > A) were shown to be associated with the risk of COVID-19 and severity in more than one observational study." (PMID 36830936, 2023). "Accordingly, VDR ApaI and TaqI variants may be associated with COVID-19 severity and long-COVID-19 symptoms in Jordanian individuals." (PMID 38138892, 2023). "We also investigated whether the VDR Fok1 (rs2228570, C/T) polymorphism could be a genetic marker for COVID-19 susceptibility." (PMID 36085364, 2023). "However, there have been few genetic investigations regarding the prevalence of VDR genetic variants and their effects on COVID-19 prognosis." (PMID 38138892, 2023). "There was an association between rs2228570 of the VDR gene and COVID-19." (PMID 37049620, 2023). "However, further research involving larger populations across multiple ethnicities is needed to assess the potential impacts of diverse VDR genetic variants on the health consequences of long-COVID-19 symptoms." (PMID 38138892, 2023). "Moreover, VDR ApaI and TaqI genotypes were significantly associated with persistent fatigue and muscle pain in a sample of Jordanian patients with COVID-19." (PMID 38138892, 2023). "Finally, the potential role of vitamin D in pathophysiology of COVID-19 should be further addressed in large-scale studies taking into account the VDR polymorphisms." (PMID 36085364, 2023). "Second, although this study included the most common VDR genetic variants, rare variants excluded from the analysis may affect VD activity and influence COVID-19 severity." (PMID 38138892, 2023). "The hypothesis was that stimulation of the VDR with calcifediol could reduce the potentially deleterious effects of respiratory distress caused by COVID-19, thus avoiding the need for admission to the ICU and mortality." (PMID 35745177, 2022).
COVID-19 (continued). "Many previous studies had reported positive links between VDR genetic variations and susceptibilities to many different inflammatory disorders, such as pulmonary tuberculosis, sepsis, and even COVID-19." (PMID 35957979, 2022). "Curiously, an association of VDR gene polymorphisms with COVID-19 outcomes has been also detected." (PMID 35650595, 2022). "However, VDR gene polymorphisms were discovered to be independently associated with the severity of COVID-19 and patient survival." (PMID 36553614, 2022). "This is consistent with the observation that low levels of vitamin D (or indeed polymorphisms in the VDR) may adversely impact the outcome of patients with COVID-19." (PMID 32946517, 2020). "The inclusion of both COVID-19 and influenza patients allows for a comparative framework for vitamin D’s potential role in different viral infections, and contributes to the literature on VDR polymorphisms, especially in influenza, where the literature is scarce." (PMID 41301713, 2025). "Furthermore, VDR activation may contribute to the regulation of the hyperinflammatory response associated with severe COVID-19 cases." (PMID 38474725, 2024). "The VDR TaqI genotype may be associated with COVID-19 severity." (PMID 38138892, 2023). "Therefore, genetic variants in vitamin D metabolism and VDR genes could be important factors in determining COVID-19 disease severity and progression." (PMID 34835935, 2021). "However, previous studies have indicated that certain polymorphisms in the VDR gene might have adverse impact on the outcome of patients with COVID-19." (PMID 34147082, 2021). "Our findings reveal a complex interplay between systemic vitamin D status, local VDR expression, and innate inflammatory mediators in COVID-19." (PMID 40904798, 2025). "Among COVID-19 negatives, VDR correlated with CCL20 (r = 0.59, p < 0.01); among positives, VDR correlated with DEFA1-3 (r = 0.45, p < 0.05)." (PMID 40904798, 2025). "Our results demonstrated the significant role of genetic variants in VDR and VDBP in the risk of COVID-19 pneumonia, mortality, and rehospitalization, confirming that vitamin D metabolism is essential in the pathology of COVID-19." (PMID 40869297, 2025). "In the COVID-19 positive group, VDR expression showed a significant positive correlation with DEFA1-3 (r = 0.45, p < 0.05)." (PMID 40904798, 2025). "This study aimed to determine how serum vitamin D status and gene expression of VDR, DEFA1-3, and CCL20 associate with COVID-19 risk in a Lebanese cohort." (PMID 40904798, 2025). "In a subset of 70 individuals stratified by COVID-19 status, we measured VDR, DEFA1-3, CCL20, and GAPDH expression by RT-qPCR." (PMID 40904798, 2025). "The gene expression comparison according to the COVID-19 disease status showed that the normalized VDR, DEFA1–3 and CCL20 expression is significantly higher in the negative group than in the positive group (P<0.05)." (PMID 40904798, 2025). "This prospective observational study aimed to assess how serum 25(OH)D concentrations and nasopharyngeal expression of VDR, DEFA1-3, and CCL20 are associated with COVID-19 status in Lebanese participants tested between January and March 2024." (PMID 40904798, 2025). "Our principal finding indicates a rapid and significant increase in VDR mRNA levels in the blood of individuals experiencing mild symptoms of COVID-19." (PMID 38474725, 2024). "In conclusion, our study unveils the intricate relationships among VDR mRNA expression, calcium levels, and iPTH concentrations in the context of post-COVID-19 vaccination." (PMID 41717585, 2024). "Our findings reveal dynamic shifts in VDR mRNA expression following COVID-19 vaccination, with distinct patterns observed across individuals." (PMID 41717585, 2024). "Here, we have documented the molecular docking and simulation analysis of the binding interactions of seocalcitol with ACE2 and VDR for further consideration in managing COVID-19." (PMID 42186536, 2024).